TNF (tumor necrosis factor)
Diseases named in the same sentence as TNF in open-access papers (continued):
Sharing a sentence is not in itself a finding about the gene and the disease.
malaria (continued). "TNF is an endogenous, pyrogenic cytokine produced by immune cells that plays a major role in malaria pathogenesis." (PMID 18369465, 2008). "In previous studies, the IL-10 (anti-inflammatory) to TNF-α (pro-inflammatory) ratio had been shown to be lower in severe malaria anaemia than in controls." (PMID 18489763, 2008). "The possible involvement of the MHC region in the genetic control of resistance to malaria resistance in humans has stimulated a search for the contribution of the MHC and TNF molecules to the pathogenesis of malaria." (PMID 18365019, 2008). "Rodent malaria parasites can activate mouse macrophages to produce the cytokines IL-12, TNF-α and MIF probably via recognition of parasite ligands by pattern-recognition receptors (PRRs)." (PMID 18439291, 2008). "The characteristics of the phospholipid fraction in paroxysm plasma are congruent with those of the malaria parasite-derived, TNF-inducing GPI moieties described by other workers." (PMID 17517147, 2007). "Another factor thought to influence clinical outcome of malaria is the fine balance between the pro- and anti-inflammatory cytokines, such as TNFα, IFNγ and IL-10 produced during the infection, that modulate parasite–induced immune responses." (PMID 17460756, 2007). "TNF-α was used to activate the monocytes because it is a major pro-inflammatory cytokine produced by macrophages of RES in children with malaria." (PMID 16879740, 2006). "The broad relevance of these malaria-origin concepts in immunity and disease is best illustrated by noting the consequence of passive vaccination against TNF for Crohn's disease and rheumatoid arthritis, now a large-scale routine treatment." (PMID 17029647, 2006). "TNF has been shown to inhibit a mouse malaria parasite in vivo, and Plasmodium falciparum in vitro, provided white cells to generate the next down-stream mediator, possibly nitric oxide, were present." (PMID 17029647, 2006). "IL-1 is known to synergize with tumor necrosis factor-α (TNF-α), and their serum levels are thought to play a role in the severity of malaria." (PMID 16098232, 2005). "It has been suggested that the bone marrow suppression is a direct effect of TNF-α, which is elevated in malaria." (PMID 16321150, 2005). "Moreover, regarding headaches in malaria, scholars showed that pro-inflammatory cytokines such as TNF-α and IL-6 have an important role in the pathogenesis of headaches in malaria." (PMID 40333915, 2025). "Consistently, TNF has been identified as a pivotal cytokine governing glucose metabolism and host energy regulation, thereby influencing disease manifestations in a murine model of malaria." (PMID 39842477, 2025). "CD4+ T cells have been demonstrated to play a central role in the immune control of Plasmodium infection, where IFN-γ- and TNF-α-producing Th1 cells are critical for controlling blood-stage malaria, while Treg cell-mediated immunomodulatory responses help limit immune-mediated host damage." (PMID 41422632, 2025). "Tumor necrosis factor-alpha and interleukin-6 levels positively correlated with parasite burden (r = 0.417, p = 0.001 and r = 0.279, p = 0.017, respectively), reflecting their roles in malaria pathogenesis." (PMID 40061813, 2025). "We demonstrate that mosquito TNF signaling via the TNF ortholog, Eiger, requires the concerted function of the receptors Wengen and Grindelwald to control several aspects of mosquito immune cell biology and that ultimately limits malaria parasite survival." (PMID 40608824, 2025). "Moreover, our data demonstrate that TNF signaling is an integral component of anti-Plasmodium immunity that limits malaria parasite survival." (PMID 40608824, 2025). "As a result, further experiments are required to define the exact mechanisms by which TNF signaling influences malaria parasite survival and whether these responses are conserved across Plasmodium species." (PMID 40608824, 2025).
malaria (continued). "Notably, cytokine levels were elevated in patients with malaria and typhoid comorbidity, particularly IL-1β, IL-2, TNF-α, and IFN-γ." (PMID 40014608, 2025). "Therefore, the present study indicates the potential impact of I. oblongifolia as an effective therapy for malaria disease, focusing on the microscopic analysis and immunobiological alterations particularly the levels of TNF-α and IL-6." (PMID 40917784, 2025). "This study indicated that TNF release, akin to fever, is paroxysmal, with a massive cytokine release occurring when a critical number of schizonts rupture simultaneously, stimulating monocytes and contributing to severe malaria pathology." (PMID 39842477, 2025). "Furthermore, frequencies of atypical MBCs had a positive correlation with serum concentrations of the proinflammatory cytokines tumor necrosis factor (TNF-α) and interleukin (IL)-8 in a cohort with a lifelong exposure to malaria." (PMID 41014333, 2025). "Thus, an excessive inflammatory response mediated by cytokines like TNF, IL-1, and IL-6 likely contributes to the tissue damage and organ dysfunction observed in severe malaria and typhoid fever." (PMID 40014608, 2025). "While cytokines such as IL-6, IL-1β, and TNF-α have been extensively studied in relation to malaria severity, the role of IL-2 in immune regulation, T cell activation, and its potential dual contributions to both protective and pathogenic responses remain less well understood." (PMID 41194029, 2025). "These receptors initiate signalling cascades that activate nuclear factor kappa B (NF‐κB), leading to increased production of pro‐inflammatory cytokines such as TNF‐α, interferon‐gamma (IFN‐γ), IL‐1β and IL‐6, all of which are implicated in the pathogenesis of malaria." (PMID 40847608, 2025). "In the malaria and typhoid fever co-morbidity group, a positive correlation was recoded between IL-2/TNFα (r = 0.515, p = 0.03), IL-2/IL-6 (r = 0.536, p = 0.02) and IL-6/TNF-α (r = 0.664, p = 0.007)." (PMID 40014608, 2025). "First, the associations between inflammatory markers and parasite counts suggest that IL-6 and TNF-α could serve as biomarkers for malaria severity and therapeutic monitoring." (PMID 40061813, 2025). "Therefore, many studies are conducted on rodent malaria to examine resistance, drug screening, and inflammatory cytokines like TNF-α, IFN-γ, and IL-10." (PMID 39204168, 2024). "Some clinical manifestations of malaria, such as fever, rigors, chills, fatigue, headache, thrombocytopenia, hypotension, anorexia, vomiting, nausea, and diarrhea, can be mimicked with an infusion of recombinant IL-1 and TNF-α." (PMID 38774541, 2024). "In addition, malaria status predicted TNF‐α, IFN‐ɣ, IL‐1β, IL‐6, GM‐CSF and IL‐10 levels, whiles anemia severity predicted only IL‐3, IL‐10 and TGF‐β levels." (PMID 39240033, 2024). "Similarly, in the UC group, the active UP-enriched pathways were found to be the IL-17 signaling pathway, Malaria, Primary immunodeficiency, TNF signaling pathway, and Viral protein interaction with cytokine and cytokine receptor." (PMID 39568749, 2024). "Significantly higher TNF-α levels were observed in patients with severe malaria." (PMID 38404582, 2024). "Malaria‐infected children had higher tumor necrosis factor alpha (TNF‐α) (p < .001), interferon‐gamma (IFN‐ɣ) (p < .001), interleukin (IL)‐1β (p < .001), IL‐6 (p < .001), granulocyte macrophage‐colony stimulating factor (GM‐CSF) (p < .001), and IL‐10 (p < .001) levels than controls." (PMID 39240033, 2024). "This suggests that rs1800890 may upregulate IL-10 transcription, with the heterozygotes potentially providing a selective advantage, as elevated IL-10 levels can down-regulate proinflammatory cytokines such as TNFα, offering protection against severe malaria." (PMID 38404582, 2024).
malaria (continued). "Since the parasite life cycle involves repeated red cell invasion and rupture, the release of pyrogenic cytokines that drive these pathways such as interleukins, interferons, and TNF in Mono and NK cells, can signify pathophysiological events occurring in malaria patients." (PMID 39830896, 2024). "Furthermore, the cytokines TNF and IL-10 have also been shown to distinguish between severe malaria anaemia (SMA) and high parasitaemia in African children." (PMID 37060041, 2023). "TNF-α is considered to be important for parasite destruction and elimination, as wellas in the development of fever and other clinical symptoms, and it also contributesto the development of severe malaria disease." (PMID 38774844, 2023). "In contrast, multigravid women had higher percentages of CD4+ T cells that produced TNFα in the absence of IFNγ, and these cells were associated with protection against malaria in pregnancy." (PMID 37634385, 2023). "In malaria infection, TNF- α is also involved in anti-Plasmodium responses that lead to intra-erythrocytic parasite killing and parasitemia reduction and it also plays a central role in the progression of malaria to cerebral malaria." (PMID 37215099, 2023). "However, TNF levels were significantly decreased in malaria coinfections (P < 0.001, MD: −16.24 pg/mL, 95% CI: −21.81–−10.67 pg/mL), I2: 98.96%, 8 studies)." (PMID 36716305, 2023). "Distinct cytokine profiles in malaria and visceral leishmaniasis coinfections were TNF and IFN-γ." (PMID 36716305, 2023). "TNF-α plays an important role in the pathogenesis and development of malaria and T2D." (PMID 37215099, 2023). "TNF-α levels has been found to be positively correlated with the severity of malaria." (PMID 37910577, 2023). "In contrast, multigravid women have a response skewed towards TNFα, and this response may correlate with protection against malaria in pregnancy." (PMID 37634385, 2023). "However, the association of TNF and IFN-γ with other pro-inflammatory cytokines is known to cause severe malaria." (PMID 38256880, 2023). "To further characterise malaria-specific nnCD4+ T cell subsets at a molecular level, we performed RNA sequencing on IL-10+IFNγ+TNFα− and IL-10−IFNγ-TNFα+ nnCD4+ T cells isolated from three DPSP primigravid pregnant women at enrolment using a cytokine capture assay (>200 cells per sample)." (PMID 37634385, 2023). "However, TNF- α is distinct among the main cytokines involved in the pathogenesis of malaria and T2D." (PMID 37215099, 2023). "Furthermore, RXR agonists, which upregulate CD36 expression through direct promoter interactions, were shown to induce an increase in CD36-mediated phagocytosis and a decrease in malaria-induced TNF-α secretion by human monocytes and macrophages." (PMID 36674699, 2023). "In pregnant women, TNF and IFN-γ were associated with the pathogenesis of severe malaria." (PMID 36668942, 2023). "Malaria-specific nnCD4 + T cells produced more TNFα in multigravid compared to primigravid women." (PMID 37634385, 2023). "As TNF-α and IL-1β could support splenic erythropoiesis in the inflammatory setting, they might also play a role in malaria-induced splenic erythropoiesis at the early stage of P. yoelii infection." (PMID 37180169, 2023). "Moreover, our KEGG analysis showed that 4 pathways were significantly different in lesional vs healthy skin of the control group, including Phagosome, Malaria, TNF signaling pathway, and Staphylococcus aureus infection." (PMID 38045687, 2023). "Malaria monoinfection exhibited high TNF and IL-12 responses." (PMID 36716305, 2023). "In addition, patients with malaria had increased PCT levels which were caused by an increase in proinflammatory cytokine levels such as interleukin-6 (IL-6), tumor necrosis factor-α (TNF-α), and interleukin-1β (IL-β) during infections." (PMID 36141662, 2022).
malaria (continued). "Additionally, TNF-α plays an important role in the pathogenesis of malaria disease, and the local accumulation and activation of macrophages can lead to severe lesions." (PMID 35214662, 2022). "Interestingly, IFN-γ and TNF-α producing CD4+ T cells play a crucial role in the protective immune response to the blood-stages of the malaria parasite in humans." (PMID 35812841, 2022). "Global analysis of lung tissues and BALF of infected mice with MA-ARDS revealed elevated levels of the cytokines and chemokines also reported in the serum of severe malaria in humans mainly, IL-1, IL-6, IL-8, IL-10, TNF-α, IFN-γ, MCP-1/CCL2, MIP-2/CXCL2, IP-10/CXCL10, KC/CXCL1, VEGF, PIGF." (PMID 35677654, 2022). "In patients with severe malaria, TNF-α production was higher than those with uncomplicated malaria." (PMID 36288040, 2022). "Our study highlights IFNγ+CD4+ T and γδ T cells co-producing IFNγ and TNF as well as anti-malarial antibodies against blood-stage proteins as correlates of varying strength of naturally acquired immunity in lifelong residents of a malaria-endemic area." (PMID 35922467, 2022). "Besides, in malaria, a TH1 type response is associated with protection such that IFN-γ and TNF-α have been observed to provide resistance against Plasmodium infection." (PMID 36211427, 2022). "Additionally, to prevent severe malaria, IL-4 and IL-10 can directly downregulate IL-6, TNF-α, and IL-1β." (PMID 35820892, 2022). "STHs would be protective against malaria according to the IL-10/TNF-α ratio, while according to the IL-10/IL-6 ratio, intestinal protozoa may have a detrimental effect." (PMID 35421083, 2022). "Studies of patients with malaria have shown P. vivax evokes relatively higher concentrations of pro- and anti-inflammatory cytokines, such as tumor necrosis factor (TNF), and other markers of host immune response than P. falciparum at similar parasite densities." (PMID 35041650, 2022). "First, the DEGs were functionally annotated, Second, these DEGs were enriched in cytokine-cytokine receptor interaction, chemokine signaling, malaria, and tumor necrosis factor (TNF) signaling, and NOD-like receptor signaling pathways upon KEGG pathway analysis." (PMID 35734177, 2022). "This suggests that the TNF-α 308 GA mutation makes a person susceptible to symptomatic malaria episodes irrespective of the level of malaria transmission in the community." (PMID 35291755, 2022). "Taken together, CD4+ T cells producing IFNγ, with or without TNF co-production, are associated with parasite control in lifelong malaria-exposed individuals." (PMID 35922467, 2022). "EBV-infected B-cells may produce TNF-α directly and high levels of TNF-α are associated with more severe Malaria." (PMID 34962938, 2021). "TNF levels were previously shown to be elevated during malaria in this cohort." (PMID 33407502, 2021). "Other previous research focused on clinical malaria, demonstrating that circulating blood samples of clinical malaria patients produced a lower cytokine response and contained less TNF-α and IL-6 producing monocytes compared to healthy controls upon stimulation with E. coli LPS." (PMID 34177883, 2021). "However, in these experiments M2 macrophages increased production of the pyrogenic cytokines IL-1β, IL-6 and TNF, and malaria-specific opsonising antibodies have been directly shown to promote inflammation in human macrophages." (PMID 33752799, 2021). "Disproportionate TNF-α production relates to the severity of Malaria and may serve as a prognostic factor." (PMID 34962938, 2021). "We observed increased levels of cytokines such as TNF-α and IL-6 in children with microscopic asymptomatic malaria, whereas, IFN-γ, IL-17A, and IL-4 levels were increased in infected children with microscopic or submicroscopic asymptomatic malaria compared with uninfected controls." (PMID 33281757, 2020). "TNF-α has been also to be important as anemia mediator in studies with malaria." (PMID 33329529, 2020).
malaria (continued). "Circulating CXCL10, CCL3, IL-8, TNF-α, and IL-6 could be used as potential biomarkers for malaria severity among individuals with hemoglobinopathies." (PMID 33424841, 2020). "Similar RNA profiles were obtained for both the CHMI subjects and symptomatic, malaria-experienced adults, with increases in IFNγ, TNFα, IL-1β, as well as the related nuclear factor kappa-light-chain-enhancer of activated B cells (NFκB) signaling and regulatory cascades." (PMID 31900030, 2020). "Similarly, in the malaria-infected donor blood, TNF-α increased progressively by 192.0% at day 7 to 433.3% at day 35 (P < 0.05)." (PMID 33195706, 2020). "In one study performed in Ghana, a high ratio of TGF-β to the pro-inflammatory cytokines IFN-γ and TNF-α correlated with increased risk of fever, but not clinical malaria presentation." (PMID 32043415, 2020). "CD4 and CD8 T cells producing IFNg, interleukin 2 (IL2) and tumor necrosis factor alpha (TNFa) were detected in peripheral blood after immunization of malaria naïve volunteers, however, their levels rapidly declined over time and were not correlated with protection." (PMID 32662772, 2020). "One study suggested that the glycosylphosphatidylinositol antigen of malaria induces monocyte and macrophage activation, resulting in the release of proinflammatory cytokines, such as tumor necrosis factor-α (TNF-α) and IL-1α, and the phagocytosis of both infected red blood cells and leukocytes." (PMID 32574170, 2020). "In the non-malaria conditions, TNF-α was significantly elevated in HbSS- compared to HbAA-." (PMID 33424841, 2020). "The up-regulated DEGs were enriched in TNF signaling pathway, cytokine–cytokine receptor interaction, and IL-17 signaling pathway, while the down-regulated genes were enriched in Malaria, Natural killer cell mediated cytotoxicity, and Calcium signaling pathway." (PMID 32436952, 2020). "Our study estimates that transfusing a 500 mL malaria-infected stored whole blood for 21 days could result in infusing 190 ng, 71.6 ng, or 48.2 ng of IL-6, TNF-α, and IL-12, respectively, to the recipient." (PMID 33195706, 2020). "The significant increases in IL-6 and TNF-α level observed in the HIV seropositive pregnant participants with malaria coinfection could be indicative of viral replication." (PMID 33193759, 2020). "Earlier reports show that TNF-α is elevated in malaria due to inflammation." (PMID 30894794, 2019). "However, a case control study in an African population with mild or severe malaria showed that both IL-10 and TNF-α were elevated in severe malaria and positively correlated with parasitemia." (PMID 30809232, 2019). "However, overproduction of pro-inflammatory cytokines (e.g., IFN-γ and TNF-α) resulted in the development of severe malaria disease." (PMID 31552201, 2019). "In the context of malaria, altered placental cytokine concentrations have been demonstrated in the presence of infection, with increased expression of both pro-inflammatory cytokine (IL-1β and TNF) and chemokines (CXCL8), and decreased expression of IL-6." (PMID 31188820, 2019). "However, it is noteworthy that other genetic modifiers of malaria susceptibility, namely NOS2, act as downstream effectors of TNF signaling encouraging further investigations on the intertwining of TNF and nitric oxide in disease development." (PMID 31417551, 2019). "However, pro-inflammatory cytokines (TNF- α, IFN-γ, IL-1 and IL-6) were associated with severe malaria." (PMID 34557294, 2019). "The exact mechanisms by which TNF is involved in severe malaria remains unknown and requires a detailed functional testing of the network of TNF-TNFR family." (PMID 31417551, 2019). "Besides, TNF-α and IL-1β levels were also found elevated during SM, similar to previous findings, which reflect the role of malaria pigment or hemozoin in the disease outcome." (PMID 31614626, 2019). "The ratio of plasma IL-10 to TNF plays an important role in determining whether children with malaria develop anemia." (PMID 30809232, 2019).